GSK3B (glycogen synthase kinase 3 beta)
Diseases named in the same sentence as GSK3B in open-access papers (continued):
Sharing a sentence is not in itself a finding about the gene and the disease.
Cognitive impairment (continued). "First, glycogen synthase kinase-3 beta (GSK-3β) induces the over-phosphorylation of Tau protein, leading to cognitive impairment." (PMID 40276552, 2025). "Measurement of GSK‐3β phosphorylation at Ser9 revealed that Exo‐cur inhibited OA‐induced activation of GSK‐3β while increased AKT expression, thereby preventing Tau phosphorylation via the AKT/GSK‐3β signaling pathway and alleviating cognitive impairments." (PMID 40949486, 2025). "Further research is needed to establish the relationship between platelet GSK-3β activation and brain GSK-3β activation, as well as its biological relations with cognitive impairment." (PMID 38660514, 2024). "In the mild cognitive impairment (MCI) stage, as the disease progresses, the dysregulation of the PI3K/Akt signaling axis and the consequent hyperactivity of GSK3β contribute to the formation of toxic tau species and the accumulation of Aβ." (PMID 39399315, 2024). "The schematic diagram showing the 9‐MF prevented long‐term cognitive impairments via cell‐specific inhibition of ROCK2 and GSK3β in APP/PS1 transgenic mice." (PMID 39563011, 2024). "GSK‐3β activation can lead to CREB‐targeted gene expression (such as BDNF) downregulation, while GSK‐3β inhibition can improve cognitive impairment." (PMID 39129397, 2024). "Other researchers revealed GM-induced hyperphosphorylation of tau through the activation of the glycogen synthase kinase 3 beta (GSK-3β) pathway, resulting in cognitive impairment." (PMID 36835459, 2023). "In this study, we verified two GSK3β inhibitors: LiCl and SB216763, we found both agents were promising for treating adolescent METH exposure-induced behavioral and cognitive deficits in adulthood." (PMID 36949769, 2023). "In order to explore the mechanism by which SQW improves STZ-induced cognitive impairment, we detected PI3K, PDK1, p-AKT, AKT, and GSK3β expression." (PMID 35741643, 2022). "Antisense oligonucleotides against GSK3β have also been tested in SAMP8 mice, which display accelerated aging along with increased Aβ levels, Tau hyperphosphorylation, neuroinflammation and cognitive deficits and have hence been used as a model of AD." (PMID 34072862, 2021). "Key biomarkers for cognitive impairment such as phosphorylation of protein kinase B (AKT) and glycogen synthase kinase-3beta (GSK-3B), were reduced by liraglutide administration in diabetic rats in a time-dependent manner." (PMID 34093449, 2021). "Insulin effectually upregulates the phosphorylation of GSK3β at Ser9 to inhibit GSK3β by enhancing the PI3-K/Akt pathway, which most likely ameliorates cognitive disorders in patients with PD." (PMID 34881082, 2021). "Through increasing the phosphorylation of AKT (AKT serine/threonine kinase 1) and GSK-3β, AM404 at low dose ameliorated cognitive deficit and reduced Aβ, Tau hyperphosphorylation, and inflammation in hyperglycemic 3×Tg-AD mice." (PMID 33196459, 2020). "To assess the effect of LiCl on GSK‐3β/β‐catenin signal channel, which is involved in cognitive impairments, we examined the protein levels of β‐catenin, JNK and GSK‐3β." (PMID 31867790, 2020). "In this study, we reported for the first time that SF ameliorated cognitive deficits induced by STZ in rats through inhibition of neuroinflammation and tau protein hyperphosphorylation via regulating the PI3K/Akt/GSK-3β pathway." (PMID 32963694, 2020). "Hence, we speculate that suppression of GSK-3β and ensuing activation of the NRF2-dependent antioxidant response is a critical mechanism underlying the protective effect of ISL against LPS-induced cognitive impairment." (PMID 31387531, 2019). "Therefore, AM404 at low dose, not only increased neuroprotection, but also ameliorated cognitive deficit, could be partly by regulating the Akt/GSK3β signaling, which may contribute to downregulation of Aβ, tau hyperphosphorylation, and inflammation in hyperglycemic 3×Tg-AD mice." (PMID 30426182, 2019).
Cognitive impairment (continued). "Thus, we propose that the suppression of hippocampal GSK-3β phosphorylation induced by the SM70EE-enhanced BDNF/PI3K/Akt signaling pathway contributes to the inhibition of APP processing by downregulating BACE1 to ameliorate the cognitive disorders induced by an I.C.V. injection of Aβ1–42." (PMID 29137190, 2017). "Furthermore, the abundance of GSK3β is increased in the frontal and temporal cortices of patients with ALS and concomitant cognitive impairment." (PMID 41546756, 2026). "Furthermore, inhibition of GSK‐3β activity using the selective inhibitor 9‐ING‐41 effectively ameliorated both AD‐like pathologies and cognitive deficits in ApoE4‐T2DM mice." (PMID 40905109, 2025). "Furthermore, the application of GSK‐3β inhibitor, 9‐ING‐41, significantly alleviated the AD‐like pathologies and cognitive deficits in ApoE4‐T2DM mice." (PMID 40905109, 2025). "Furthermore, the abundance of GSK3β is also increased in the frontal and temporal cortices of patients with ALS and concomitant cognitive impairment." (PMID 40502782, 2025). "GSK3β inhibition was observed in response to trehalose, which upregulated ERα and ERβ and protected APP/PS1 mice against dietary advanced glycation end product (dAGE)-induced neurotoxicity and cognitive impairment." (PMID 38064105, 2024). "MN:Ameliorates cognitive deficits.Suppresses neuroinflammation and synaptic dysfunction.Inhibits Aβ deposition.Modulates PI3K/Akt/GSK-3β and NF-κB pathways.Improves cognitive function through increased expression of synaptic proteins and anti-inflammatory cytokines." (PMID 39459209, 2024). "Widely used to induce memory or cognitive deficits in rodent models for dementia-related studies, scopolamine-driven neurodegeneration in rats is reported, including increased Aβ protein, APP mRNA levels, phosphorylated tau, and GSK-3β levels." (PMID 38397402, 2024). "Although several chemosynthetic GSK‐3β inhibitors exist in clinical trials for patients with cognitive impairment, none of the compounds are used clinically." (PMID 39129397, 2024). "Elevated GSK‐3β has been found in the periphery platelet of T2DM patients with mild cognitive impairment (MCI) compared with those without MCI." (PMID 37700547, 2023). "Furthermore, abnormal BDNF permeability and cognitive impairment were observed in older mice, correlated with increased TLR4 expression and decreased phosphorylation of serine 9, an inhibitory residue in GSK-3β protein." (PMID 38001481, 2023). "Our previous studies also showed that L‐NBP improved cognitive impairment in an APP/PS1transgenic AD mouse model might through inhibitory effects of CDK‐5 and GSK‐3β signaling pathways." (PMID 35445545, 2022). "In addition to GSK-3β, the role of protein kinase A (PKA) in hippocampus Tau phosphorylation and neuroinflammation-related cognitive deficits has been confirmed in animal AD models." (PMID 35993019, 2022). "GSK3 includes GSK3α and GSK3-β, of which GSK3-β is considered a key participant in AD pathophysiology, and imbalances in the kinase affect the hyperphosphorylation of tau protein, cognitive impairment, neurogenesis, synaptic function, and apoptosis induced by Aβ over deposition." (PMID 36124291, 2022). "Similarly, blockade of GSK-3β by antisense oligonucleotides ameliorated AD symptoms in SAMP8 mice, a mouse model that displays increased Aβ levels, tau hyperphosphorylation, and cognitive deficits." (PMID 35126052, 2021). "How exactly the platelet GSK-3β activation may reflect brain GSK-3β activation and its biological relations with cognitive impairment deserve further investigation." (PMID 34746146, 2021). "In the present study, our data for the first time revealed that MN could ameliorate the cognitive deficits in TgCRND8 transgenic mice via inhibition of neuroinflammation and synaptic dysfunction through modulating the PI3K/Akt/GSK-3β and NF-κB pathways." (PMID 32714487, 2020).
Cognitive impairment (continued). "In summary, our results demonstrated that SF, a Raphani Semen-derived isothiocyanate, was able to ameliorate cognitive impairments induced by STZ in rats partially via inhibiting neuroinflammation and hyperphosphorylation of tau protein through modulating the PI3K/Akt/GSK-3β pathway." (PMID 32963694, 2020). "We then highlight evidence suggesting that GSK3β influences hippocampal volume in MDD patients, and how this could assist with targeting more precise treatments particularly for cognitive deficits in patients with mood disorders." (PMID 30310078, 2018). "However, APAP attenuated the reduction by phosphorylating GSK3β in the hippocampus and blocked GSK-3β activity in response to LPS, thus providing protection from LPS-induced apoptosis and cognitive impairment." (PMID 28109286, 2017). "GSK‐3β inhibitors hold therapeutic potentials for T2DM and AD possibly by preventing the aggregation of β‐amyloid (Aβ), inhibiting the hyperphosphorylation of tau protein, or reducing neuroinflammation in animal models, but their effectiveness for improving cognitive impairment need further proof." (PMID 37700547, 2023). "We next asked whether REST induction in aged individuals with no cognitive impairment (NCI) but with early AD pathology is associated with repression of CDK5 and GSK3β." (PMID 37919281, 2023). "Polysaccharides isolated from P. ostreatus ameliorated cognitive impairment induced by D-Gal and Al in an AD rat model by decreasing Aβ formation and tau phosphorylation via elevation of PP2A expression and reduction of APP, glycogen synthase kinase 3beta (GSK3β), and BACE-1 expression." (PMID 36432520, 2022). "We observed that KXS upregulated AKT phosphorylation, suppressed GSK3β and CDK5 activation, and inhibited the TLR4/MyD88/NF-κB signaling pathway to attenuate Tau hyperphosphorylation and neuroinflammation, thus suppressing neuronal apoptosis and improving the cognitive impairment of aged SAMP8 mice." (PMID 35303280, 2022). "Thus, in this study, we used the CUMS model to investigate the antidepressant-like activity and cognitive impairment effects of SCE, moreover, the BDNF/TrkB/ERK/CREB and PI3K/AKT/GSK-3β signaling pathways were determined to illustrate the action mechanism of SCE." (PMID 28761074, 2017). "Together, the results suggested that in 7,8-DHF-treated group, significant differences were found in the expression of p-TrkB, p-AKT, and p-GSK3β, which suggested that 7,8-DHF might play a role in ameliorate cognitive impairment in ApoE-KO mice by regulating AKT/GSK3β pathway." (PMID 27965573, 2016). "In addition to its ability to reduce Aβ production and tau phosphorylation, Rps23rg1/RPS23RG1 overexpression attenuates oAβ-induced synaptic and cognitive impairments by restoring PKA activity, which subsequently leads to enhanced CREB activity and decreased GSK-3β activity and tau phosphorylation." (PMID 26733416, 2016). "Our results suggested that the therapeutic effects of aripiprazole on the negative symptoms and cognitive deficits of schizophrenia might be attributed to its inhibiting effects on GSK3β activity in the PFC." (PMID 27435909, 2016). "However the use of lithium, a non-specific inhibitor of GSK3β results in mild cognitive impairment in humans." (PMID 26157370, 2015). "However, whether and how ApoE4 exacerbates cognitive deficits through GSK‐3β in T2DM conditions are not known." (PMID 40905109, 2025). "This suggests that the cognitive impairment of AD mice may be related to the insulin signaling pathway, and DSS intervention may reduce the accumulation of neuropathological products by regulating the IRS1/GSK3β/Wnt‐β‐catenin pathway, thus playing a cognitive protective role." (PMID 39344343, 2024).
Cognitive impairment (continued). "The “GSK3 hypothesis in AD” suggests that the overactivation of GSK-3β is closely related to several features of the pathology of AD, including microglia-mediated inflammation, Aβ production, APP processing, tau phosphorylation, neuronal death, and cognitive deficits." (PMID 32714487, 2020). "Therefore, chronic systemic administration of AM404 at low dose used maybe reverse cognitive deficits via Akt/GSK3β pathway, not dependent on a direct GSK3β inhibitor, CB1, or TRP1 receptor in hyperglycemic 3×Tg-AD mice." (PMID 30426182, 2019). "Therefore, whether antipsychotics control the negative symptoms and cognitive deficits of schizophrenia via the enhancement of Akt-GSK3β signalling requires further validations." (PMID 27435909, 2016). "Very recently, studies have shown that GSK3β mediated tau phosphorylation has an important role in LTD and is reported to be dysregulated in cognitive disorders including AD and a non-pathological model." (PMID 26687096, 2016).
colon carcinoma (168 papers, 2010 to 2026). "Inhibiting GSK-3β has been associated with a reduction in cancer cell growth across several types of malignancies, including prostate, and colon cancers and leukemia." (PMID 41039321, 2025). "In this prior work, the effects in prostate and colon cancer cells were consistent with the role of FRAT1 in preventing the association of GSK-3β with the destruction complex, while the downregulation of PAK4 inhibited nuclear translocation of β-catenin." (PMID 38815861, 2024). "GSK3α was more closely associated with colon cancer progression and unfavorable outcomes than GSK3β." (PMID 37031867, 2023). "Enhanced GSK-3β expression in colon carcinoma samples was associated with resistance to 5-FU and in vitro inhibition of GSK-3β abolished cell viability via necroptosis and reduced xenograft growth in vivo." (PMID 26248051, 2015). "In this regard, GSK3β is constitutively activated in colon cancer cells, where it is implicated in tumorigenesis and cancer progression." (PMID 23527181, 2013). "Therefore, the GSK3β inhibitor can cause mitotic catastrophe in colon cancer cells." (PMID 35884370, 2022). "TBX21 inhibits the proliferation of colon cancer cells through an ARHGAP29/RSK/GSK3β-dependent mechanism." (PMID 39744435, 2025). "Akt is a key player in the growth of colon tumors; it stops GSK3β/APC/axin from breaking down β-catenin and increases the expression of oncogenes like c-Myc and cyclin D1 that target β-catenin." (PMID 39811247, 2025). "(2014), an increase in ROS generation was demonstrated at different concentrations of LiCl in SW-480 colon cancer cells (a different cell line from the one used in our study) through the ROS/GSK-3β/NF-κB pathway, thereby suppressing cell proliferation." (PMID 41303707, 2025). "FBXW7 and GSK3β overexpression reduces CDX2 levels and function, causing growth arrest in colon cancer cells; disruption of both CDX2 phosphodegrons prevents FBXW7-mediated degradation." (PMID 41373479, 2025). "Considering our results that show increased inhibitory phosphorylation of GSK3β (pSer9-GSK3β) under IBU treatment, we suggest that IBU-mediated inhibition of GSK3β influences COX-2 expression in hypoxic colon cancer and head and neck cancer cell lines." (PMID 40408503, 2025). "This study provides novel insights into how NRXN1 influences colon cancer progression and highlights potential avenues for targeted therapy through the modulation of downstream signals, such as GSK3β inhibitors." (PMID 39518976, 2024). "Hesperidin triggered cell death in colon cancer-afflicted mice by suppressing the ongoing activation of the Aurora-A-driven PI3K/Akt/GSK-3β and mTOR pathways, thereby stimulating autophagy in this particular colon cancer model." (PMID 39201782, 2024). "Our findings show that NRXN1 functions as a TSG in colon cancer and suggest that GSK3β inhibition is a promising therapeutic option in the context of NRXN1 knockdown; however, further validation studies are needed." (PMID 39518976, 2024). "CLDN1 upregulation after exposure to conventional chemotherapies used in colon cancer is, at least in part, functionally related to activation of the MAPKp38/GSK3β/Wnt/β-catenin pathway." (PMID 39065798, 2024). "Another study in colon cancer cells revealed that RSV reversed the EMT process through AKT/GSK-3β/SNAIL signaling." (PMID 37446730, 2023). "Evidence also suggests that celastrol attenuates the growth of human colon cancer cells via blocking the PI3K/AKT/GSK3β pathway." (PMID 36895009, 2023). "In colon cancer, lithium reduces the expression of transforming growth factor-β-induced protein (TGFBIp) by inhibiting Smad3 phosphorylation through GSK3β inhibition." (PMID 36836894, 2023). "EpEX binds to HGFR and induces tumor progression and metastasis through ERK and FAK-AKT by inducing HGFR activation and GSK3β-Snail and β-catenin signaling in colon cancer cells." (PMID 37543570, 2023).